PITX1 (paired like homeodomain 1)
Diseases named in the same sentence as PITX1 in open-access papers (continued):
Sharing a sentence is not in itself a finding about the gene and the disease.
dysplasia (1 paper, 2014). A usually neoplastic transformation of the cell, associated with altered architectural tissue patterns. "The PITX1 LI of the dysplasia specimens was significantly lower than that of the normal oral mucosa samples, but significantly higher than that of the OSCC samples." (PMID 24527083, 2014).
Esotropia (1 paper, 2021). A form of strabismus with one or both eyes turned inward ('crossed') to a relatively severe degree, usually defined as 10 diopters or more. "In this way, an up-regulation of PITX1 has the potential of inhibiting differentiation within the lateral rectus muscle of the paralytic esotropia group." (PMID 34044792, 2021). "The results of RT-PCR revealed that PAX7, MYOG, PITX1, SIX1 and SIX4 showed higher levels of expression, while that of MYOD a lower level of expression within the paralytic esotropia group as compared with that in the control group (p < 0.05)." (PMID 34044792, 2021).
hypothyroidism (1 paper, 2021). Abnormally low levels of thyroid hormone. "Finally, induction of Pitx2 deficiency in thyrotropes using Tshb-cre causes moderate growth deficiency, blunted TSH response to hypothyroidism challenge, and elevated Pitx1 expression." (PMID 33858413, 2021). "Mice with a pituitary-specific disruption of Pitx2 exhibit elevated Pitx1 expression in response to induced hypothyroidism, suggesting functional compensation." (PMID 33858413, 2021).
invasive breast carcinoma (1 paper, 2020). A carcinoma that infiltrates the breast parenchyma. "The co-expression profile of PITX1 was identified with a large cluster of 12,624 measured genes across 103 invasive breast carcinomas, the nucleotide-binding oligomerization domain 2 (NOD2) is a principal co-expression gene." (PMID 32830857, 2020).
leiomyoma (1 paper, 2022). A well-circumscribed benign smooth muscle neoplasm characterized by the presence of spindle cells with cigar-shaped nuclei, interlacing fascicles, and a whorled pattern. "The promoter regions of NPAS4 and PITX1 genes were selected as the candidate methylation marker loci to distinguish uterine leiomyosarcoma and leiomyoma." (PMID 35875106, 2022).
liver disease (1 paper, 2022). "A biomarker panel consisting of HMMR, NXPH4, PITX1 and THBS4 was defined and validated as an effective serologic diagnostic tool for the detection of HCC patients among liver disease patients through the use of simple ELISAs." (PMID 35456219, 2022).
lupus (1 paper, 2022). "Recent RNA-sequencing data of SLE skin have identified another transcription factor, PITX1, which facilitates hypersensitive responses to type I IFNs in lupus keratinocytes." (PMID 35721085, 2022).
oral epithelial dysplasias (1 paper, 2014). "The PITX1 LI was 72.8±6.5, 52.3±9.24 and 4.8±4.25 [mean ± standard deviation (SD)] in the normal oral mucosa, oral epithelial dysplasia and OSCC samples, respectively." (PMID 24527083, 2014). "In the present study, PITX1 expression was examined in oral epithelial dysplasia, which is considered to be a precancerous lesion of OSCC." (PMID 24527083, 2014). "PITX1 and Ki-67 expression were assessed by immunohistochemistry in 26 individuals with normal oral mucosa, 106 patients with oral epithelial dysplasia and 97 OSCC patients." (PMID 24527083, 2014). "In the high-grade group, the PITX1 LI was 53.4±2.75 (median ± SE) for malignant transformation-negative oral epithelial dysplasia and 26.1±3.53 for malignant transformation-positive oral epithelial dysplasia." (PMID 24527083, 2014). "The present study was the first to report a correlation between PITX1 and oral epithelial dysplasia." (PMID 24527083, 2014). "Immunohistochemical analysis showed that PITX1-positive cells were distributed in the basal cell layer of the normal oral mucosa and in numerous oral epithelial dysplasia samples." (PMID 24527083, 2014). "The mean PITX1 LI of the oral epithelial dysplasia samples was significantly lower than that of the normal oral mucosa specimens, but significantly higher than that of the OSCC samples (P<0.001)." (PMID 24527083, 2014). "In addition, PITX1 may serve as a novel biomarker for predicting prognosis in oral epithelial dysplasia." (PMID 24527083, 2014). "In the low-grade group, the PITX1 LI was 52.6±0.94 [median ± standard error (SE)] for malignant transformation-negative oral epithelial dysplasia and 33.3±4.85 for malignant transformation-positive oral epithelial dysplasia." (PMID 24527083, 2014). "By contrast, it was found that PITX1 downregulation was significantly more common in malignant transformation-positive oral epithelial dysplasia cases than in malignant transformation-negative cases, independent of the histological grade of dysplasia." (PMID 24527083, 2014). "Immunohistochemical analysis showed that the malignant transformation-negative oral epithelial dysplasia cases were detected for PITX1 nuclear staining." (PMID 24527083, 2014). "The PITX1 LI was 52.3±8.40 (mean ± SD) in the cases of oral epithelial dysplasia that did not undergo malignant transformation (P<0.01) and 29.4±9.40 in those that did, and the difference was significant (P<0.01)." (PMID 24527083, 2014). "The median PITX1 LI was significantly decreased in malignant transformation-positive oral epithelial dysplasia, regardless of the histological grade of the dysplasia." (PMID 24527083, 2014). "The oral epithelial dysplasia patients that exhibited low PITX1 expression showed a significantly higher incidence of malignant transformation than those exhibiting high PITX1 expression, regardless of the histological grades of their oral epithelial dysplasias." (PMID 24527083, 2014).
pituitary adenoma (1 paper, 2022). "Consistent with the histologic differentiation, the M6 pituitary adenoma showed massive upregulation of POU1F1 and PITX1, high overexpression of PITX2 and NR4A1-3, but minimal or absent expression of TBX19 and NR5A1, respectively." (PMID 35978432, 2022).
prostate tumors (1 paper, 2022). "Tissue slides of a comprehensive set of more than 15,000 prostate tumors showed that a low or high level of PITX1 was associated with a poorer prognosis compared to PITX1 negative status." (PMID 35267575, 2022). "In summary, we observed that PITX1 protein and gene expression in primary prostate tumors correlate with longer telomeres." (PMID 35267575, 2022).
psoriasis (1 paper, 2022). An autoimmune condition characterized by red, well-delineated plaques with silvery scales that are usually on the extensor surfaces and scalp. "Of these nine regulators, four regulators (STAT3, FOXE1,PITX1,TFD) did not overlap with the top 30 regulators of AD, we consider these four regulators as key regulators for psoriasis." (PMID 35874668, 2022).
pterygium (1 paper, 2021). A wedge-shaped fibrovascular lesion arising from the bulbar conjunctiva and extending to the cornea. "We found that genes encoding transcription factors MYC, KLF4, POU5F1 and PITX1 were upregulated in pterygium." (PMID 34769520, 2021). "POU5F1 is one of the top upregulated genes in pterygium as is a second transcription factor PITX1." (PMID 34769520, 2021). "This analysis suggests an expansion of cells from the corneal limbal epithelial compartment in pterygium, and identifies KLF4, MYC and POU5F1 and PITX1 as specifically involved." (PMID 34769520, 2021).
tumor (48 papers, 2008 to 2026). "Lastly, our 75 collection of clinical patient tissue samples exhibited varying levels of PITX1 expression across different cancer grades while also demonstrating a significant association with tumor differentiation and metastasis." (PMID 40342824, 2025). "PITX1 expression in tumor samples associated with (i) increased Ki67 expression indicating increased tumor growth, (ii) a worse prognosis, and (iii) correlated with telomere length." (PMID 35267575, 2022). "Hypermethylation of PITX1 was associated with tumor depth (P = 0.0011) and advanced tumor stage (P = 0.0052) and predicted poor survival in ESCC (hazard ratio, 0.1538; 95% confidence interval, 0.03159–0.7488; P = 0.0169)." (PMID 29137437, 2017). "By intersecting the DEG sets of all three groups, we identified a shared PITX1 gene that may be associated with tumor differentiation." (PMID 40342824, 2025). "However, a statistically significant association was observed between PITX1 expression and both tumor differentiation (p<0.001), as well as metastasis (p=0.042)." (PMID 40342824, 2025). "PITX1 expression was associated with tumor stage and survival outcomes." (PMID 40342824, 2025). "Differential and correlation analyses indicated that three types of tumor-infiltrating cells exhibited differential expression patterns that were significantly associated with PITX1 expression levels (naive B cells, follicular helper T cells, activated NK cells)." (PMID 40342824, 2025). "Moreover, the Student’s t-test values indicated that PITX1 was significantly associated with tumor stage, histologic grade, and N stage, which are related to cancer progression." (PMID 36204311, 2022). "The PITX1 gene (encoding paired-like homeodomain 1) has been reported as a tumor suppressor and may be involved in the tumorigenesis of multiple human cancers, including CRC." (PMID 24968322, 2014). "Therefore, PITX1 has been implicated as a tumor suppressor in various cancers." (PMID 35456219, 2022). "Gene differential expression analysis revealed a strong correlation between PITX1 expression and tumor grade." (PMID 40342824, 2025). "PITX1 is considered a tumor suppressor gene, and is known to influence the expression of GH1, and is related to IGF-1." (PMID 40951278, 2025). "The PITX1 regulon is activated in all tumor cells except that its activity is stronger in T1 than in other subpopulations." (PMID 39223689, 2024). "PITX1+ Anagen HF cells showed activation of proliferation, growth, and hyperplasia ontologies while the HF Stem Cells had immune response, tumor-related, and fibrosis/death-related ontologies activated." (PMID 39480496, 2024). "In a study focused on KIRC, miR-886-3p demonstrated heightened expression, while PITX1 appeared to be underexpressed as a tumor suppressor gene." (PMID 37841446, 2023). "Cellular and functional investigations underscore PITX1’s potential dual nature as an oncogene and a tumor suppressor, warranting comprehensive research and further exploration." (PMID 37841446, 2023). "We sought the mechanisms of the anti-tumor effects induced by PITX1 by screening its targets genes using RNA sequencing." (PMID 36334221, 2023). "PITX1 dramatically inhibited tumor growth, based on reduced tumor size and weight compared with the control group." (PMID 36334221, 2023). "PITX1 (Paired Like Homeodomain 1), as a tumor suppressor, was proven to be a direct target of miR-675, and its downregulation led to EMT stimulation through Wnt/β-catenin signaling." (PMID 37386429, 2023). "Specific knockdown of LINC00662 reduced the tumor growth and invasion of OS cells induced by downregulated PITX1." (PMID 36334221, 2023). "Curiously, an alternate investigation analyzed PITX1 expression in KIRC through TCGA, TIMER, and GEO databases, finding high mRNA expression levels in tumor tissues alongside hypermethylated PITX1 DNA." (PMID 37841446, 2023).
tumor (continued). "The expression of PITX1 exhibits tumor-type specific variation, and it functions as a tumor suppressor gene in several human cancer types." (PMID 37841446, 2023). "treated tumor cells with DNA damaging agents, such as mitomycin C and etoposide, resulting in a significant increase in PITX1 expression levels." (PMID 37841446, 2023). "The expression of PITX1 was significantly correlation with tumor-infiltrating CD8+ T cells (Rho = −0.15, p = 8.56e−04), CD4+ T cells (Rho = 0.166, p = 2.22e−04), macrophages (Rho = −0.248, p = 2.36e−08), and DCs (Rho = −0.207, p = 3.83e−06)." (PMID 36204311, 2022). "As for tumor immune infiltration, PITX1 and PITX2 expression was positively correlated with the infiltration of Th17 cells and Act_CD8+ T cells, but negatively correlated with NKT cell infiltration." (PMID 36204311, 2022). "In summary, PITX1 expression in tumor samples suits as a biomarker for the prognosis of PCa progression, particularly in combination with the pre-operative variables PSA, Gleason grade from biopsies, and tumor stage." (PMID 35267575, 2022). "For 34 samples (of n = 17 patients in duplicate), images were tiled and telomere and PITX1 intensities were considered on tumor regions specified by a pathologist." (PMID 35267575, 2022). "The findings of this study revealed that PITX1 has a multifunctional role in tumor suppression, such as in the regulation of telomerase activity and the SOX signaling." (PMID 34526609, 2021). "Our results revealed that PITX1 mRNA was overexpressed in tumor tissues compared with normal tissues in the TCGA-KIRC database (p < 0.001) and numerous independent cohorts (p < 0.05)." (PMID 34868397, 2021). "Bicoid-related PITX genes are shown to be responsible for cell survival, and PITX1 functioned as a tumor suppressor in hepatocarcinogenesis." (PMID 35071766, 2021). "Among the sites, both cg02948884 and cg04101060 are in the GpC island of PITX1 (paired-like homeodomain), a tumor-suppressor gene." (PMID 32441304, 2020). "De novo PITX1 expression in tumor-propagating cells controlled self-renewal and proliferation through co-binding with SOX2 and TRP63 and repressing KLF4, which maintains differentiation, in murine SCC." (PMID 33202305, 2020). "Previous reports indicate that the hypermethylation of the PITX1 correlated with the tumor progression HNSCC and ESCC." (PMID 31490960, 2019). "According to a post- GWAS study and genome-wide meta-analysis, the PITX1 gene functions as a tumor suppressor gene related to CRC carcinogenesis." (PMID 29484135, 2018). "Recently, pituitary homeobox 1 (PITX1) was reported to act as a tumor suppressor in hepatocarcinogenesis by activating the expression of p120RasGAP (also known as Ras p21 protein activator 1 (RASA1)), triggering Ras inactivation by converting GTP into GDP." (PMID 29558404, 2018). "Both PITX1 exon 3 and lincRNA C5orf66-AS1 were significantly higher methylated in tumor tissue than in normal adjacent tissue (NAT) (PITX1 exon 3: tumor tissue 58.1%, NAT: 31.7%, p<0.001; lincRNA C5orf66-AS1: tumor tissue: 27.4%, NAT: 18.9%, p<0.001)." (PMID 29425237, 2018). "Both PITX1 exon 3 and lincRNA C5orf66-AS1 were significantly higher methylated in tumor tissue than in normal adjacent tissue (PITX1 exon 3: tumor tissue 58.1%, NAT: 31.7%, p<0.001; lincRNA C5orf66-AS1: tumor tissue: 27.4%, NAT: 18.9%, p<0.001)." (PMID 29425237, 2018). "Methylation and expression of both PITX1 mRNA and lincRNA C5orf66-AS1 were significantly associated with tumor location, p16 expression, HPV-status and complete resection (R0)." (PMID 29425237, 2018).
tumor (continued). "Another noteworthy observation is that DNA hypermethylation of PITX1 correlated with advanced tumor size, advanced tumor stage, and a poor postoperative prognosis." (PMID 29137437, 2017). "Although PITX1 methylation may correlate with total epigenetic alteration of many genes, which is associated with the phenotypes of clinically advanced tumor cells, our studies clearly demonstrate that PITX1 methylation status of the tumor could be used as a clinical marker to predict prognoses." (PMID 29137437, 2017). "Hypermethylation of PITX1 clearly correlated with advanced tumor size, advanced tumor stage, and a poor prognosis, suggesting the possibility of the methylation status of PITX1 as prognostic markers of ESCC." (PMID 29137437, 2017). "The most likely involved gene PITX1 (paired-like homeodomain 1) has been considered to be a tumor suppressor gene relating to carcinogenesis of CRC and other cancers." (PMID 26381143, 2015). "Adding to its role as a tumour suppressor gene is a recent study that identified PITX1 as a negative regulator of telomerase reverse transcriptase, an enzyme critical for the unlimited replication characteristic of tumour cells." (PMID 24369427, 2014). "Although a role in development has been the primary focus of PITX1 studies, several recent reports suggest an additional role as a tumour suppressor gene." (PMID 24369427, 2014). "Additionally, we conducted differential expression analysis, immune cell infiltration assessment, and immune checkpoint analysis on pan-cancer datasets to determine the effect of PITX1 on tumor-infiltrating cells (TICs) across various cancer types." (PMID 40342824, 2025). "Our results indicate that PITX1 may potentially inhibit tumor progress and kill tumors by recruiting NK and B cells while reducing Treg infiltrate in CHS." (PMID 40342824, 2025). "To explore whether PITX1 exhibits a similar tumor grade-related characteristic in other cancer types as observed in CHS, we analyzed tumor grade and gene expression across various cancer types." (PMID 40342824, 2025). "We identified significant variations in PITX1 expression across 14 tumor types." (PMID 40342824, 2025). "In addition, the expression level of NOTCH1 and PITX1 was lower in the tumor tissue of smoking patients compared to the tumor tissue of nonsmoking patients." (PMID 38540309, 2024). "Regarding the expression of EMT biomarkers, it was found that elevated PITX1 significantly increased the expression of E-cadherin and decreased the expression of β-catenin and vimentin in OS cells, indicating that PITX1 inhibits tumor cell adhesion and EMT." (PMID 37841446, 2023). "All results demonstrated a tumor suppressor role for PITX1 in OS." (PMID 36334221, 2023). "This comprehensive review delves into the multifaceted role of PITX1 in tumor formation." (PMID 37841446, 2023). "However, the authors did not specify the mechanism by which PITX1 induces this abnormal proliferation function, as most studies have identified PITX1 acted as a tumor suppressor gene." (PMID 37841446, 2023). "Although PITX1 exhibits promise as a clinical tumor marker, a series of enigmas remain unsolved." (PMID 37841446, 2023). "In addition, the expression of the SMAD3 and PITX1 downstream targets can accurately segregate GB from LGG in a panel of >600 TCGA tumour samples." (PMID 37833281, 2023). "Besides, the expression level of PITX1 was determined in 32 paired normal and ESCC patient tissue samples, and a significant decrease in PITX1 expression was observed in tumor tissue." (PMID 37841446, 2023).